LEP (leptin)
Diseases named in the same sentence as LEP in open-access papers (continued):
Sharing a sentence is not in itself a finding about the gene and the disease.
Obesity (continued). "To further assess the possible implication of these strong candidate genes (GRIK1, GRM7, GRPR and SLCO4C1), we determined the co-expression patterns between them and 15 well-defined genes from the leptin-melanocortin pathway previously related to obesity." (PMID 28489853, 2017). "Leptin is one of the most abundant adipokines secreted by adipocytes, which is positively corelated with obesity, diabetes and insulin resistance." (PMID 29057818, 2017). "As variation in dopamine function contributes to obesity through alterations in energy expenditure and activity, changes in this system via differences in leptin modulation can potentially be involved in the current findings." (PMID 29186804, 2017). "This medium containing a series of mediators secreted by adipocytes is thought to be closer to the physiology of obesity than the medium with leptin supplement alone." (PMID 28182687, 2017). "Some of the monogenic obesity genes which manifest as severe obesity in children are leptin (LEP), leptin receptor (LEPR), pro-opiomelanocortin (POMC), and prohormone convertase 1 (PCSK1)." (PMID 28924523, 2017). "Leptin plays a critical role in human pathophysiology of a group of diseases because it elicits considerable interest in its potential in treating obesity and insulin resistance." (PMID 28348585, 2017). "Mc3rTB/TB mice are hyperleptinemic owing to obesity, however a decline in plasma leptin concentrations during HFS was still observed; meal-related increases were observed irrespective of genotype, but were more pronounced in Mc3rTB/TB mice." (PMID 28294152, 2017). "Patients with fibromyalgia and overweight/obesity presented lower levels of leptin than controls with overweight/obesity." (PMID 28226002, 2017). "In conclusion, we identify MYT1Lmutations as a cause of syndromic obesity, and establish MYT1L as a member of the leptin-melanocortin-SIM1 pathway, with downstream loss of OXT associated with MYT1L mutations a potential therapeutic target." (PMID 28859103, 2017). "First, as also stated by the authors, numerous factors are strictly related with serum leptin levels including obesity, insulin, glucocorticoids, and thyroid hormones via multiple signaling pathways." (PMID 28890432, 2017). "These mainly include genes that are involved in energy balance, appetite regulation, and adipogenesis, i.e., fat mass and obesity-associated protein gene (FTO), and genes in the leptin–proopiomelanocortin pathway and uncoupling protein families." (PMID 28615046, 2017). "In cases of metabolic dysfunction, like obesity, leptin resistance can occur eliminating a positive signal to the reproductive axis." (PMID 28623929, 2017). "SH2B1 is an activator of leptin signaling, and deletions or mutations in the SH2B1 gene are associated with severe obesity in humans and mice." (PMID 28912580, 2017). "Circulating leptin and insulin are also detected to be elevated in other types of obesity such as induced by high-fat diet, idiopathic, and in patients with Cushing’s disease." (PMID 28101317, 2017). "The largest network included 20 proteins and was predicted to be involved in tissue morphology, inflammatory response and cardiovascular diseases including proteins encoded by genes already associated with obesity (INS, LEP, SERPINE1, IL1RAP, and RARRES2)." (PMID 29234017, 2017). "Circulating levels of leptin, an adipocyte-secreted hormone, are decreased or increased in undernutrition or obesity, respectively, and have thus been proposed to be a link between nutritional status and immune function." (PMID 28348560, 2017). "Further, we reported that the neonatal leptin peak was eliminated by maternal overnutrition/obesity in MO lambs." (PMID 28771488, 2017). "In a gene-induced obesity diabetic model, leptin secretion increased along with increasing fat, but adiponectin secretion decreased, leading to an increase in the leptin/adiponectin ratio." (PMID 29109369, 2017).
Obesity (continued). "Adiponectin and leptin have evolved as crucial signals in many obesity-related pathologies including non-alcoholic fatty liver disease (NAFLD)." (PMID 28758929, 2017). "Leptin resistance defines a state of obesity where hyperleptinemia or diminished responsiveness to this hormone is observed." (PMID 28771179, 2017). "Hypothalamic inflammation decreases satiety response to insulin and to the adipocyte-derived hormone leptin, which can contribute to positive energy balance and development of obesity." (PMID 29156608, 2017). "We also give an overview of the pleiotropic factors involved in the regulation and dysregulation of the homeostatic hypothalamic system in the context of obesity, including hypothalamic inflammation as well as insulin and leptin resistance." (PMID 28592656, 2017). "Cross-talk and redundancy between these signals complicate the precise assessment of the contribution of leptin-mediated signaling in the context of leptin resistance and obesity." (PMID 28270795, 2017). "Rodent models of impaired leptin functionality show progressive obesity due to exaggerated food intake." (PMID 28542631, 2017). "During obesity, the cerebrospinal fluid/serum leptin ratio is decreased, indicating impairment of leptin transport." (PMID 28270795, 2017). "Yet, with increasing obesity, tissues can become insensitive to Leptin which is thought to contribute to the progression of obesity." (PMID 28256596, 2017). "Obesity in many currently used pre-clinical animal models, is mediated by a monogenic disruption in leptin signaling or is initiated by high fat feeding (DIO models)." (PMID 28640904, 2017). "The crossing of these two strains and the selective inbreeding for obesity, insulin resistance and hyperglycemia has resulted in an inbred strain exhibiting obesity in the presumed presence of an intact leptin pathway." (PMID 28640857, 2017). "Leptin, an adipocyte-derived protein, has emerged as a key player in the pro-inflammatory process in obesity and metabolic syndrome and is, therefore, considered a pivotal link in obesity-related diseases." (PMID 29176959, 2017). "Bi-allelic SNVs of leptin (LEP), leptin receptor (LEPR), and pro-opiomelanocortin (POMC) are also associated with hyperphagic obesity." (PMID 28859103, 2017). "Leptin resistance also occurs from increased caloric intake, and under fasting conditions, elevated serum leptin levels are proportional to the mass of adipose tissue and increase obesity-induced leptin resistance resulting in hyperleptinemia." (PMID 29104232, 2017). "Although the relationships among adipokines, obesity, and disease states is complex, these results provide evidence that sex steroid hormones are involved in the regulation of leptin transcription and protein synthesis and its sexual dimorphism." (PMID 28811502, 2017). "The results of the study support the existence of the relationship among vitamin D, obesity and leptin in type 2 diabetic patients." (PMID 29295491, 2017). "Evidence from animal studies also suggests that HFD-induced obesity results in higher concentrations of serum leptin, insulin, and insulin-like growth factor-1 (IGF-1), and facilitates colon tumor formation." (PMID 28170448, 2017). "A leptin-resistant state has been demonstrated in obesity and obesity-related cardiovascular disease." (PMID 29021828, 2017). "Insufficient sleep physiologically increases levels of ghrelin and decreases levels of leptin, which can affect appetite regulation and contribute to the development of obesity." (PMID 28713808, 2017). "The interacting role of overweight body habitus and obesity in youth with BSD further indicates leptin resistance to be a central moderator of the dynamic neurobiology of BSD in youth." (PMID 29093685, 2017). "Adipose tissue (AT) has a modulating role in obesity-induced metabolic complications like type 2 diabetes mellitus (T2DM) via the production of so-called adipokines such as leptin, adiponectin, and resistin." (PMID 28686216, 2017).
Obesity (continued). "The high circulating levels of leptin during obesity lead to the chronic activation of intracellular JAK-STAT3 signaling, which further induces the expression of SOCS3." (PMID 29025435, 2017). "To summarize, key drivers of obesity-related bone phenotype were sex-specific: significant independent effects of leptin on bone characteristics were marked in males, while in females hs-CRP displayed an independent role." (PMID 28640843, 2017). "Our data indicate that maternal exposure to ambient PM2.5 programs obesity in male offspring probably through alterations in the methylation of the promoter region of the leptin gene." (PMID 28645299, 2017). "The discovery of leptin in 1994 generated high expectations for its potential use as a therapeutic to combat obesity." (PMID 28270795, 2017). "According to previous findings, plasma leptin concentration is directly related to the degree of obesity and is higher in women than in men of the same body mass index." (PMID 28369078, 2017). "It catalyzes the de-phosphorylation of activated insulin receptor, and hence downregulates insulin signalling, additionally it also negatively regulates leptin signalling and contributes to obesity and metabolic disorders." (PMID 28933230, 2017). "Leptin is a crucial regulator of energy expenditure and caloric intake, and numerous studies have correlated obesity to altered leptin metabolism." (PMID 29089667, 2017). "Serum concentrations of insulin, insulin-like growth factor-1 (IGF-1), leptin, and adiponectin were measured as obesity-related phenotypic markers." (PMID 28170448, 2017). "Compounds like gingerol have earlier been shown to have anti-obesity action and are reported for their beneficial influence on lipid profile, insulin, leptin, amylase and lipase in obese rats." (PMID 28804442, 2017). "The discovery and cloning of leptin and the leptin receptor were widely hoped to provide a solution to the problem of obesity." (PMID 28350856, 2017). "Even though several compounds with anti-obesity properties have been identified, studies on natural compounds which can inhibit the oncogenic role of leptin and target leptin signaling pathway/s are limited." (PMID 28930270, 2017). "In both the LEP and LEPR genes, homozygous mutations have been described that derive in extreme obesity." (PMID 28771179, 2017). "Xbp1s (spliced X-box binding protein 1) is one of the ER-stress-induced genes and neuron-specific Xbp1−/− mice have ER stress, severe hyperleptinemia, leptin resistance, and obesity." (PMID 28270795, 2017). "Leptin and adiponectin are adipose-derived factors with particular interest due to their potential as therapeutics in obesity treatment." (PMID 28348560, 2017). "SH2B1 enhances leptin signaling through the augmentation of JAK2 activity, and deletions or mutations in the SH2B1 gene are known to be associated with severe obesity in humans and mice." (PMID 28912580, 2017). "Leptin secreted by adipocytes suppresses food intake and stimulates energy expenditure and its levels are increased with adipogenesis and obesity." (PMID 29258500, 2017). "Increased MyD88 signalling in the hypothalamus has been found to contribute to fatty acid induced leptin resistance and diet induced obesity." (PMID 29190946, 2017). "While we do not see a change in hypothalamic Kiss1 gene expression the changes in LH and FSH prior to obesity onset point towards impaired central leptin signaling." (PMID 28357399, 2017). "People with overweight and obesity have higher leptin concentrations but often become leptin resistant." (PMID 28747890, 2017). "High levels of circulating leptin in adipose tissues characterize human obesity and increased levels of body fat." (PMID 28854906, 2017). "The obese (ob/ob) mouse, a long-standing model of human obesity, gained favor for leptin studies after Freidman’s laboratory cloned the truncated LEP gene." (PMID 28443063, 2017).
Obesity (continued). "ATGLi mice are resistant to HFD-induced obesity, exhibit lower plasma leptin and elevated adiponectin levels, and show reduced inflammation in WAT when compared with untreated control mice on HFD." (PMID 28327588, 2017). "Similarity of the oncogenic lipid kinase (SPHK1) to leptin has led many studies done on the relationship between this gene, obesity, and breast cancer; although these mechanisms and pathways were linked with poor prognosis." (PMID 29531546, 2017). "The heterozygous SOCS3-deficient mouse was more sensitive to the weight-reducing effects of leptin and was resistant to the development of diet-induced obesity." (PMID 28881823, 2017). "How changes in leptin signaling contribute to obesity is certainly complex, with interacting endocrine, neurological, epigenetic, and environmental variables." (PMID 28443063, 2017). "TLR signaling is known to promote obesity-induced resistance to insulin and leptin, suggesting that upregulation of Peli3 in response to HFD is implicated in the increased serum concentrations of insulin and leptin observed in the present study." (PMID 28170448, 2017). "Additional research to characterize the abnormal secretome of leptin-deficient HSC is justified, given the steadily rising prevalence of obesity-related liver disease in the general population." (PMID 28427343, 2017). "Consistently, global Cc1−/− null mice develop elevated production and secretion of leptin from their expanded while adipose depot in addition to increased total fat mass and obesity resulting from hyperphagia and reduced spontaneous physical activity." (PMID 28184213, 2017). "Plasma leptin concentration was significantly higher in subjects with obesity than in the normal-BMI subjects, whereas adiponectin was lower." (PMID 28771179, 2017). "Leptin resistance, in which leptin signaling is disrupted, is a major obstacle to the improvement of obesity." (PMID 28912580, 2017). "Leptin, adiponectin, and insulin are indicators of body mass fats and energy imbalance and are present in obesity." (PMID 29234430, 2017). "While an increasing number of adipokines are implicated in the development of the obese phenotype, the focus of this review will include MCP-1, IL-6, TNF-α, IL-1β, leptin and adiponectin as the key mediators of AT inflammation and dysfunction in obesity." (PMID 29186929, 2017). "We found unaltered Dusp6 mRNA levels in various brain areas of mice subjected to substantial metabolic challenges such as leptin injections, diet–induced obesity or prolonged fasting and refeeding." (PMID 28873424, 2017). "Formula-fed infants had a different profile of ARH than breastfed infants, suggesting that lower levels of ghrelin, leptin and insulin in breastfed infants contribute to the protective role of breastfeeding against obesity development." (PMID 27170102, 2017). "The obesity-related inflammatory models of macrophage were built using leptin, Ad-CM, and a co-culture system." (PMID 28182687, 2017). "In the perspective of obesity and cardiovascular disease, the predictive power of the 16 kDa adipokine leptin and the 30 kDa cardioprotective adiponectin seems most relevant to study." (PMID 28747890, 2017). "For example, leptin plays a crucial role in maintaining glucose metabolism, and adiponectin protects against obesity-related complications by enhancing fatty acid oxidation and insulin sensitivity." (PMID 28574439, 2017). "The role of overweight/obesity and adipokines in fibromyalgia is more complex than a linear relationship between obesity, leptin production, and more severe pain." (PMID 28226002, 2017). "Leptin is one of the major adipokines, its increased level indicates the severity of fat accumulation in obesity." (PMID 28809927, 2017). "Leptin resistance appears to be a mechanism contributing to the burden of obesity that extends across multiple organs." (PMID 28428959, 2017).
Obesity (continued). "Because endospanin is highly conserved, it represents an opportunity to study leptin sensitivity across models and an avenue to explore for human obesity treatment." (PMID 28443063, 2017). "As leptin imposes an overall inhibitory action on VTA LepR neurons, resistance to diet-induced obesity by VMAT2 deletion is in line with a general role of leptin-inhibited neurons such as AgRP neurons." (PMID 28560316, 2017). "CRF-OE showed a blunted reduction of leptin in both sexes by fasting which was also observed in diet-induced obesity (DIO) mice exposed to a prolonged fast (48 h) and in Zucker (fa/fa) rats." (PMID 28101317, 2017). "Body weight, wet weight of isolated white adipose tissue, and obesity-related serum parameters (glucose, lipids, leptin, adiponectin) were measured after treatment." (PMID 28360931, 2017). "We aimed to review the literature on the effects of physical training on peripheral leptin level as indicator of metabolic health in obesity during aging." (PMID 28809927, 2017). "There is an emerging need to clarify the impacts of obesity and adipose tissue-produced adipokines (leptin, adiponectin, kisspeptin) in pregnancy." (PMID 28409493, 2017). "At last, our data support the evidenced strong relationship between leptin and adiponectin as well as their modulation by BMI and dietary pattern diet; the linkage between leptin resistance and obesity was confirmed, too." (PMID 28408969, 2017). "Mice lacking ROCK1 in either POMC or NPY/AgRP neurons, display impaired leptin sensitivity and obesity." (PMID 28270795, 2017). "Insulin resistance and obesity are characterized by a low-grade but chronic inflammatory state, with elevated circulating levels of CRP, TNF-α, IL-6 and leptin and reduced ACDC concentrations associated with increased cardiometabolic risk." (PMID 29020958, 2017). "Human obesity has also been described as a state of leptin insensitivity, as high levels of food intake and body adiposity occur despite very elevated circulating leptin concentrations." (PMID 29312147, 2017). "This study supports a role of mineralocorticoid receptor in the cardiac fibrosis induced by leptin in the context of obesity and highlights the role of the mitochondrial ROS in this process." (PMID 29196758, 2017). "In particular, obesity programming of the offspring has been postulated to occur periconceptionally and at the end of pregnancy, when an increase in lipid and leptin expression is observed." (PMID 29283404, 2017). "According to a review of these models they are remarkably similar with polygenic obesity, maturity onset diabetes and moderate leptin resistance." (PMID 28640857, 2017). "Fructose metabolism cannot be controlled by insulin or leptin, which are key factors for the regulation of fat synthesis and energy intake hence, obesity will likely be the consequence." (PMID 28129400, 2017). "Studies conducted in both humans and DIO mouse model clearly showed that, during obesity, the higher level of Leptin concentration correlated with SNA in renal nerves and blood pressure increase." (PMID 28590409, 2017). "A GWAS which identified 14 known obesity susceptibility variants and 18 new loci that were associated with BMI found that some of these loci are mapped at the LEP–POMC pathway, i.e., LEP and its receptor LEPR, POMC and MC4R." (PMID 28615046, 2017). "In the present study, we are the first to identify differential beta oscillatory activity and coherence in the limbic cortico-basal ganglia loop in obesity that is strongly correlated with serum insulin and leptin levels." (PMID 29138510, 2017). "We find that obesity due to chronic exposure to a high fat diet impairs sensing of leptin (as measured by STAT3 phosphorylation in response to exogenous leptin) throughout the brain, which is congruent with similar studies in rodents and humans." (PMID 28107353, 2017).